ATG7 (autophagy related 7)
Diseases named in the same sentence as ATG7 in open-access papers (continued):
Sharing a sentence is not in itself a finding about the gene and the disease.
tumor (continued). "In individuals where inherited and somatic ATG7 variants are discovered, preclinical mouse studies suggest that the genetic state of well‐characterised oncogenes and tumour suppressors should also be investigated." (PMID 34725936, 2021). "In genetically engineered mouse models (GEMMs) that yield BrafV600E- and Pten-deficient melanomas, tumor-specific ablation of Atg7 resulted in accumulation of defective mitochondria and impaired tumor growth." (PMID 32878084, 2020). "Atg7 and Lkb1 loss sensitize tumor-derived cell lines (TDCLs) to metabolic stress, suggesting that autophagy inhibition can be a favorable approach for the treatment of Lkb1-deficient lung tumors." (PMID 32878084, 2020). "Loss of the autophagy-related gene Atg7 in intestinal epithelial cells was shown to attenuate tumor growth driven by loss of adenomatous polyposis coli (APC), a major tumor suppressor in colorectal cancer." (PMID 33381037, 2020). "Pten and Atg7-autophagy loss in GEMMs revealed tumor-promoting effects of autophagy in castrate-naïve and castrate-resistant prostate cancers (PCa)." (PMID 32878084, 2020). "Accumulation of lipid droplets and defective mitochondria by Atg7 deficiency attenuated Ras-driven tumor proliferation." (PMID 33381037, 2020). "This is demonstrated in a mouse lung cancer model where Atg7 deletion, which causes a block in autophagy, initially accelerated tumour growth, and however at later stages caused a decrease in tumour burden and ultimately an increase in survival." (PMID 32745353, 2020). "Simultaneous loss of p62 or Nrf2 in mice with livers deficient in Atg7 or Atg5 suppresses tumor development 91, 94, implying that the p62‐mediated activation of Nrf2 contributes to tumor growth in autophagy‐deficient mouse livers." (PMID 30499183, 2019). "Treg cells-specific deletion of Atg7 or Atg5, two essential genes in autophagy, leads to loss of Treg cells, further tumor resistance, and inflammatory disorders." (PMID 30678689, 2019). "In mouse models, loss of Atg7 in intestinal epithelial cells inhibited tumor growth through an immune response elicited by the microbiome." (PMID 31671556, 2019). "Ras-mutated tumours have shown an increased dependency on the autophagic process in vitro and in vivo, and knockdown of autophagy-related genes Atg5 and Atg7 limited tumour growth." (PMID 30182146, 2018). "Deletion of Atg 5 and Atg7 causes spontaneous formation of benign liver tumours, further suggesting a role for autophagy in tumour suppression." (PMID 30182146, 2018). "In mice possessing an oncogenic allele of Kras, ablation of Atg5 and Atg7 prevented further tumor development." (PMID 28725634, 2017). "For example, the deletion of Beclin 1, ATG5, or ATG7 were found to associate with the tumor phenotype of HCC." (PMID 28915706, 2017). "For instance, in a prostate-specific Pten-deficient mouse model, additional knockout of autophagy-related-7 (Atg7) markedly delayed tumor development under both castration-naïve and castration-resistant conditions." (PMID 27303918, 2016). "While ATG-7 is often implicated in tumor initiation and progression, its functional profile is highly context dependent, reflecting the dualistic nature of autophagy as both a tumor-suppressive and tumor-promoting process." (PMID 41550506, 2026).
tumor (continued). "For example, studies using a genetically engineered mouse model with conditional deletion of Atg5 or Atg7 resulted in significant suppression of tumor growth, indicating the tumor-promoting role of autophagy, which was associated with impaired glucose homeostasis in lung tumors." (PMID 40214497, 2025). "Further, we investigated whether HMGCR targeting could improve the ATG7-deficient inducing anti-tumor efficacy of anti-PD-1." (PMID 38627815, 2024). "For example, in a mouse CT26 colon tumor model, mitoxantrone and oxaliplatin activate autophagy and enhance tumor-infiltrating dendritic cells and T cells, and depletion of autophagy-associated proteins (ATG5 or ATG7) reduces chemotherapy-induced anti-tumor immune responses." (PMID 35740594, 2022). "Tan and colleagues observed that autophagy was increased in hypoxic regions of tumors in three different human tumor cell lines and hypoxia-induced cell death was more rapid in their autophagy-deficient variants with shRNA knockdown of the genes ATG7 and BECLIN1." (PMID 35686268, 2022). "Neoplasia has been found in the liver and pancreas of various autophagy-deficient mouse models, including Becn1 heterozygous mice, systemic mosaic Atg5 deletion mice, and liver- or pancreas-specific Atg5 or Atg7 deletion mice." (PMID 35646940, 2022). "Furthermore, ATG7 deficiency results in an accumulation of defective mitochondria and affects tumor fate, as adenomas and carcinomas become more benign oncocytomas." (PMID 35883626, 2022). "Likewise, deficiency of core autophagy genes like Atg7, Atg5, and Fip200 represented tumor suppression effects." (PMID 34365465, 2021). "As the Atg-5 and Atg-7 genes are related to autophagosome formation, the deletion of the Atg-5 gene in mice can cause the development of multiple benign tumors in the liver, and the liver-specific deletion of Atg-7 in mice also induces tumor production." (PMID 35155196, 2021). "Moreover, supplementation with arginine in Atg7-deficient mice model partially relieved arginine reduction and tumor growth inhibition." (PMID 33510635, 2020). "Additionally, in mice with Kras-driven lung tumors, Atg7 deficiency reduced tumor burden but developed macrophage and lymphocyte infiltration and an extreme inflammatory response." (PMID 31554173, 2019). "Mice deficient in ATG5 and liver-specific deletion of ATG7 develop benign liver adenomas, supporting the notion that autophagy may be tumour suppressive at the beginning of tumourigenesis." (PMID 31878323, 2019). "Similarly, loss of Atg7 in intestinal epithelial cells and tumor tissue led to infiltration of anti-tumor immune cells decreasing tumor burden." (PMID 31671556, 2019). "In addition, ATG7 deficiency can completely inhibit tumor occurrence and development of intestinal epithelial cells in mice." (PMID 29311760, 2018). "Similarly, the Atg7 deficiency in mice with BRAF-induced lung tumor also resulted in accumulation of dysfunctional mitochondria ultimately leading to tumor growth restriction." (PMID 29643976, 2018). "Also other autophagy-involved proteins, such as UV radiation resistance-associated gene (UVRAG), Atg5, and Atg7, were recently described as tumor suppressors." (PMID 28725634, 2017). "Therefore, our hypothesis posited that ATG7 inhibition to impede cholesterol accumulation would cause anti-tumor immune response activation." (PMID 38627815, 2024). "Interestingly, a strikingly similar observation to the situation in those tumours is found in the case of the Dictyostelium prespore pathway; mutations such as atg7 that reduce the efficiency of autophagy virtually eliminate prespore gene expression while not affecting prestalk gene expression." (PMID 34820379, 2021). "However, Atg7-deficient mice with p62-deficient hepatocytes showed decreasing in tumor size." (PMID 28915706, 2017).
tumor (continued). "Endothelial-specific Atg7 knockout was induced via tamoxifen administration, initiated the day after tumor inoculation, to ensure knockout during the formation of the tumor vascular network." (PMID 39744218, 2025). "However, induction of deficient autophagy through deletion of Atg5 or Atg7 in mice leads to benign liver tumors, indicating that autophagy could play an essential role in inhibiting tumor initiation in liver, which necessitates further research in human cancers." (PMID 40248706, 2025). "Some, such as ATG7, function as tumor suppressors, whereas oncogenic factors like Ras and signal transducer and activator of transcription 3 are frequently overexpressed in breast cancer and contribute to tumor progression." (PMID 40384989, 2025). "Atg7 silencing resulted in significant inhibition of tumor growth as compared to control mice (shCtrl)." (PMID 40611330, 2025). "Liver-specific deletion of Atg7 produced circulating arginase and reduced both serum Arg levels and tumor growth." (PMID 41249150, 2025). "Although the importance of autophagy in PDAC has been demonstrated by the tumor-suppressive effects of Atg5 and Atg7 deletion, the role of ULK1, a key initiator of autophagy, remains underexplored in in this context." (PMID 41408407, 2025). "In breast cancer models, it is reported that ATG7 gene is essential for autophagy instigation in dormant tumor cells." (PMID 40444035, 2025). "Deletion of Atg5 or Atg7 in KRasG12D-driven spontaneous lung cancer models reduced tumor size compared with that in wild type (WT) mice." (PMID 41408407, 2025). "It reduced PD-L1 and Rab11 content of TEX, altered tumor cell size/shape, induced vesicle accumulations in the cytosol, and upregulated expression levels of autophagy-related proteins, ATG7, Beclin-1, and LC3." (PMID 40121518, 2025). "Herein, we observed that clone A of Atg5‐overexpressed Atg7−/− MEF cells induced larger tumor size compared to positive control M5R cells at day 3 p.i., followed by rapid regression." (PMID 38826147, 2024). "Intriguingly, overexpression of Atg5 in autophagy‐deficient Atg7−/− MEF stable clones significantly increased cell proliferation, colony formation, and cell migration in vitro, and transiently promoted tumor formation in vivo." (PMID 38826147, 2024). "We demonstrated their role in the PTT-induced execution of autophagy that progressed through ATG5/ATG7, which was reversed and increased the survival of tumor cell populations by silencing them." (PMID 39409987, 2024). "For example, the immunosuppressive effect of Tregs is highly autophagy dependent, and ATG5 or ATG7 deletion in T cells induces severe tumor implantation rejection in isogenic mouse tumor models." (PMID 38918278, 2024). "It has been found that miR-93 mimics target ATG7 and increase the resistance to cabergoline; however, miR-93 inhibitors decrease tumor growth and increase the efficacy of cabergoline against prolactinoma in vivo." (PMID 39702128, 2024). "On the one hand, liver‐specific deletion of ATG5 or ATG7 was reported to induce benign hepatomas, suggesting a role for autophagy in tumor suppression." (PMID 39166458, 2024). "Regarding ceRNA networks, CLRN1 antisense RNA 1 (CLRN1-AS1)/miR-217/ Dickkopf-related protein 1 (DKK1) and H19/miR-93a/autophagy related 7 (ATG7) are the identified tumor suppressive ceRNA that suppresses miR-217 and miR-93a, respectively." (PMID 39702128, 2024). "Meanwhile, ATG7 inhibition also suppressed cholesterol accumulation and augmentation of anti-tumor immune responses." (PMID 38627815, 2024). "Change in ATG7 levels is not only observed in H1792 cells; the immunoblotting of heterotopic H1792 tumor tissue lysate shows a nominal degree of enhanced ATG7 staining in mice treated with AM-101." (PMID 39335139, 2024). "A series of experiments indicated that in early tumorigenesis, the tumor- suppressive role of autophagy changes into pro-tumorigenic function due to genetic perturbation, such as deletion of Atg7 Atg7 in mice." (PMID 38846985, 2024).
tumor (continued). "The effects of shATG7 and ATG7-IN-1 treatment in immunocompromised mice (BALB/c-Nude mice) were examined to assess the effect of adaptive immunity on ATG7-mediated tumor growth and tumor weight reduction." (PMID 38627815, 2024). "ATG7 inhibition restored surface major histocompatibility complex I (MHC-I) levels, causing improved antigen presentation and anti-tumor T cell response by activating reactive oxygen species (ROS)/NF-κB pathway." (PMID 38627815, 2024). "Inhibition of ATG7 enhanced the anti-tumor immune response in CRC, as evidenced by increased MHC-I expression via the ROS/NF-κB signaling pathway." (PMID 38627815, 2024). "The promotion of autophagy, BC cells proliferation, and tumor growth is facilitated by the interaction between circCDYL and miR-1275 targeting the ATG7/ULK1 axis." (PMID 39281375, 2024). "It has been reported that the suppression of ULK1, Atg7, and Atg13 favours a reduction in tumour growth." (PMID 37174088, 2023). "The tumor cells with high level of lnc‐FSD2‐31:1 expression combined with ATG7‐depleted CAFs were injected into pancreas of nude mice." (PMID 36727832, 2023). "Collectively, these results suggest that lnc‐FSD2‐31:1 in tumor cells induces ATG7‐dependent autophagy and suppresses fibrosis in CAFs, which contribute to antitumor efforts in PDAC." (PMID 36727832, 2023). "Consistent with the in vitro study, we also found that the protein expression of LC3-II and ATG7 was increased while p62 was decreased in tumor tissues from C. tropicalis -treated CRC mice compared to control group." (PMID 37476193, 2023). "In the second batch, lnc‐FSD2‐31:1‐depleted tumor cells with ATG7‐overexpressed CAFs were introduced." (PMID 36727832, 2023). "The acetylated FoxO1 binds to Atg7 in the cytosol, leading to the induction of autophagy, autophagic cell death, and tumor suppression in vitro and in vivo." (PMID 37762548, 2023). "Suppressing autophagy by deleting ATG5 or ATG7 will prevent malignant tumor formation and slow the development of the tumor." (PMID 37108476, 2023). "Various mechanisms have been proposed based on tumor conditions or the microenvironment, but most involve Atg5 or Atg7." (PMID 38067169, 2023). "Our findings that the depletion of ATG7 abrogates the inhibitory effects of PSMD2 knockdown on ESCC cell proliferation indicate that the tumor-promoting roles of PSMD2 in ESCC depends on its activity to inhibit autophagy." (PMID 36998052, 2023). "Meanwhile, all the mRNAs enriched in autophagy pathway were verified via qRT–PCR, and only ATG7 mRNA expression in CAFs was positively correlated with the lnc‐FSD2‐31:1 level in tumor cells." (PMID 36727832, 2023). "In whole-body Atg7 or Atg5 KO mice, circulating arginine levels are decreased, resulting in suppressed tumor growth." (PMID 35646940, 2022). "On the one hand, mice with allelic loss of Beclin1 are tumor prone and liver-specific deletion of ATG5 or ATG7 induces benign hepatomas, which suggest a role for autophagy in tumor suppression." (PMID 35600411, 2022). "We then analyzed the relationship between expression of ATG7 and tumor purity in HNSCC using the TCGA database." (PMID 36262348, 2022). "Next, the association of L/P@Ferritin-induced tumor cell death and cellular autophagy was probed, L/P@Ferritin nanoparticles caused a more significantly increase of LC3B-II and Atg7." (PMID 35725558, 2022). "The GO items showed that ATG7 was highly involved in the tumor immune microenvironment in HNSCC, including chemokine activity, MHC protein procession, and neutrophil activation." (PMID 36262348, 2022). "The deletion of Atg7 in a model of K-ras(G12D)-driven non-small-cell lung cancer reduced tumor burden." (PMID 36429119, 2022).
tumor (continued). "In a KRASG12D-driven NSCLC mouse model, ablation of ATG7 leads to a suppression of proliferation, thus decreasing tumor growth." (PMID 35883626, 2022). "ATG7 was negatively correlated with tumor purity (r = −0.038, P < 0.001), suggesting a positive correlation between high ATG expression and high infiltrating immune cells in HNSCC tumors." (PMID 36262348, 2022). "In summary, our findings uncover autophagy-independent roles of ATG7 in both the repression of primary tumor development and in the promotion of metastasis and cellular invasion." (PMID 35867735, 2022). "Conversely, in the case of ATG7, we found that the wildtype ATG7 allele was deleted in the tumor and thus the haplotype with the ATG7 germline mutation (p.R659*) was retained, leading to loss of heterozygosity (LOH) in tumor." (PMID 35725745, 2022). "Our finding that Atg7 hemizygosity affects tumor progression, metastasis, and cellular invasion in an autophagy-independent manner highlights significant diverse roles for ATG7." (PMID 35867735, 2022). "In an oncogenic KRAS-driven non-small cell lung cancer (NSCLC) mouse model, deleting Atg7 specifically in tumor cells reduced the tumor burden compared to that in mice with Atg7-expressing NSCLC." (PMID 35147163, 2022). "The abrogation of Atg7 diminished tumor growth to different extents in these two models of skin carcinogenesis." (PMID 36429119, 2022). "In this study, we found that treatment with taxifolin increased the expression of autophagy-related proteins including LC3B-II, Atg7, atg12, and Beclin-1 suggesting that the autophagic pathway was activated in our tumor model." (PMID 34462635, 2021). "Our results are in contrast to work from Xie and colleagues who found that Atg7-deletion prevents tumour formation in the context of Pten deletion." (PMID 33664481, 2021). "This discovery is particularly interesting given the prominent liver phenotypes, including tumour formation, observed in Atg7‐null mice." (PMID 34725936, 2021). "Attenuating ATG7 function to sensitise tumour cells to cancer treatments has also been investigated in preclinical models with some success." (PMID 34725936, 2021). "In MCC tumor, low expression of ATG7 and p62 are correlated with MCPyV-positive tumor, suggesting the importance of autophagy evasion in MCPyV-associated tumorigenesis." (PMID 34745965, 2021). "The combination treatments also enhanced the reduction of the proliferation marker Ki67 and the induction of apoptosis marker PARP cleavage and ATG7, which is induced to mediate autophagy under glucose deprivation, in the xenograft tumor tissues." (PMID 34155348, 2021). "It was reported that Beclin1−/− mice die early in embryogenesis and aging; mice with Beclin1+/− are tumor-prone, whereas mice with Atg5−/− and Atg7−/− are born normally, but die soon due to low nutritional level and suckling defects in neonates." (PMID 33628386, 2021). "For instance, inhibiting autophagy by genetical deletion of ATG7, an essential autophagy gene, suppressed tumor growth in the KRASG12D-driven NSCLC mouse model." (PMID 34461934, 2021). "Such a role was supported by studies showing that targeting BECN1, ATG5, and ATG7 promotes tumor initiation." (PMID 33718194, 2021). "In KrasG12D-driven lung tumor cell, the deletion of Atg5 or Atg7 reduces cell proliferation and tumor burden, suggesting that this is due to impaired autophagy." (PMID 33292489, 2020). "In lung tumors, Atg7 has already been identified as an important factor for sustained tumor cell proliferation at later stages." (PMID 32046105, 2020). "Immunoblot analysis of Cyclin E also showed a higher level in tumor and non-tumor regions of the Atg7ΔHep livers than that in the Atg7/Hmgb1ΔHep livers." (PMID 32382012, 2020).